DSCR9 (Down syndrome critical region 9)
Synonyms: NCRNA00038
Gene: Long non-coding RNA gene on chromosome 21 (37,208,196 to 37,237,353, forward strand). Ensembl gene ENSG00000230366.
Diseases named in the same sentence as DSCR9 in open-access papers:
DSCR9 is named in the same sentence as 13 diseases in open-access papers, as found by Europe PMC text mining. Sharing a sentence is not in itself a finding about the gene and the disease. The quoted sentences say what the papers report.
Down syndrome (4 papers, 2010 to 2022). "Here, we developed a multi-step bioinformatics analysis to study the functions of a particular Down syndrome-associated gene DSCR9 including the lncRNAs." (PMID 29351810, 2018). "After mining the RNA expression data from Affymetrix transcriptional profiling microarrays, the functions of the DSCR9 lncRNA were found to be enhanced in neurological-related pathways, which might cause Down syndrome and other neurological diseases." (PMID 29351810, 2018). "We therefore hypothesize that genetic variants in DSCR9 or nearby genes may influence the aggregation of connective tissue of normal iris resulting in different iris color appearance, and extreme forms of variation, e.g., via trisomy, lead to Down Syndrome." (PMID 20463881, 2010). "lncRNA DSCR9 is transcribed from the Down syndrome critical region (DSCR) of chromosome 21." (PMID 36789695, 2022). "DSCR9 was highly correlated with genes that were known as important factors in the developments and functions of nervous system, indicating that DSCR9 may regulate neurological proteins regarding Down syndrome and other neurological-related diseases." (PMID 29351810, 2018). "We identified the regulation function of DSCR9, a lncRNA transcribed from the Down syndrome critical region (DSCR) of chromosome 21, by analyzing its co-expression genes from over 1700 sets and nearly 60,000 public Affymetrix human U133-Plus 2 transcriptional profiling microarrays." (PMID 29351810, 2018). "The SNP at the 21q22.13 locus was within the Down Syndrome Critical Region in a high LD region containing the TTC3 and DSCR9 genes." (PMID 22383892, 2012).
breast carcinoma (1 paper, 2019). "After survival analysis and ROC curve analysis of each DERNA, eight lncRNAs (AC104472.1, PSORS1C3, DSCR9, OSTN-AS1, AC012074.1, AC005035.1, SIAH2-AS1, and ERVMER61-1) and one mRNA, SPOPL, were identified as prognostic factors in breast cancer." (PMID 31572452, 2019).
diverticulosis (1 paper, 2023). "In the MA GWAS for diverticulosis, rs2835676 (DSCR9 gene) showed strong eQTL association with both transverse and sigmoid colon tissues within the PIGP and TTC3 genes (FDR<3.90E-13)." (PMID 37196047, 2023).
hypercoagulability (1 paper, 2024). "Among these, lncRNA DSCR9 (lncDSCR9 or DSCR9) was identified, which is a differentially expressed lncRNA implicated in inflammation and hypercoagulability." (PMID 39376558, 2024). "A co-culture model of RA PBMCs and RA-FLSs was established to demonstrate the effects of lncRNA DSCR9 on RA inflammation and hypercoagulability." (PMID 39376558, 2024).
lung carcinoma (1 paper, 2018). "Additionally, gastrin-releasing peptide receptor (GRPR) was also identified as an important target candidate of DSCR9, and diseases that associated with GRPR include lung cancer and prostate adenocarcinoma." (PMID 29351810, 2018).
pancreatic carcinomas (1 paper, 2022). "Here, we demonstrate that the lncRNA DSCR9 is an important factor associated with the prognosis of pancreatic cancer patients." (PMID 36789695, 2022). "Herein, the expression of DSCR9 was markedly decreased in pancreatic carcinoma tissue samples and cell lines." (PMID 36789695, 2022). "DSCR9 expression was also significantly downregulated in four pancreatic carcinoma cell lines, PANC-1, BxPC-3, MIAPaCa-2, and AsPC-1, compared to that in the human pancreatic nestin-expressing cell line hTERT-HPNE." (PMID 36789695, 2022). "Under gemcitabine treatment, DSCR9 overexpression increased, whereas miR-21-5p overexpression decreased cell apoptosis; miR-21-5p overexpression significantly reversed the effects of DSCR9 overexpression on pancreatic cancer cell apoptosis." (PMID 36789695, 2022). "Forced overexpression of DSCR9 in pancreatic cancer cells inhibited the proliferation and invasive ability of cancer cells while enhancing gemcitabine-induced apoptosis, suggesting that DSCR9 has a tumor-suppressive effect on pancreatic cancer." (PMID 36789695, 2022). "In conclusion, we demonstrated that the lncRNA DSCR9/miR-21-5p/BTG2 axis modulates pancreatic cancer proliferation, invasion, and resistance to gemcitabine." (PMID 36789695, 2022). "DSCR9 overexpression significantly enhanced gemcitabine-induced effects on the apoptosis of both pancreatic cancer cell lines." (PMID 36789695, 2022). "In contrast to DSCR9 overexpression, miR-21-5p overexpression enhanced the aggressiveness of pancreatic cancer cells by promoting the proliferation and invasive ability of cancer cells and attenuating gemcitabine-stimulated apoptosis." (PMID 36789695, 2022). "Before investigating the specific effects of DSCR9 on pancreatic cancer cell phenotypes, we further explored the correlation of DSCR9 expression with the prognosis of patients with pancreatic cancer based on TCGA-PAAD database." (PMID 36789695, 2022). "In conclusion, the DSCR9/miR-21-5p/BTG2 axis modulates pancreatic cancer proliferation, invasion, and gemcitabine resistance." (PMID 36789695, 2022). "DSCR9 overexpression significantly inhibited the proliferation and invasion of pancreatic cancer cells while enhancing apoptosis under gemcitabine treatment." (PMID 36789695, 2022). "In this study, we found that lncRNA DSCR9 is downregulated in pancreatic cancer, and can modulate pancreatic cancer cell proliferation, invasion, and resistance to gemcitabine through lncRNA/miRNA/mRNA axis." (PMID 36789695, 2022). "CCK-8, BrdU and flow cytometry assays show that overexpression of DSCR9 markedly suppresses pancreatic cancer cell proliferation and invasion, and promotes apoptosis under gemcitabine treatment." (PMID 36789695, 2022). "To investigate the mechanism of DSCR9 function in pancreatic cancer cells, we further analyzed online data to select DSCR9-related factors." (PMID 36789695, 2022). "The functions of the lncRNA DSCR9/miR-21-5p/BTG2 axis in new pancreatic cancer treatment strategies await further investigation." (PMID 36789695, 2022). "Thus, the DSCR9/miR-21-5p axis regulates the proliferation, invasion, and gemcitabine resistance of pancreatic carcinoma cells via BTG2." (PMID 36789695, 2022). "Since BTG2 has been reported to be targeted by several miRNAs within pancreatic carcinomas, such as miR-21 and miR-27a, we speculate that there might be other miRNAs mediating the crosstalk between DSCR9 and BTG2 in pancreatic cancer cells." (PMID 36789695, 2022). "More importantly, the tumor-suppressive effects of DSCR9 overexpression on pancreatic cancer cells were significantly reversed by miR-21-5p overexpression, whereas the suppressive effects of DSCR9 overexpression on BTG2 expression were reversed by miR-21-5p overexpression." (PMID 36789695, 2022).
pancreatic carcinomas (continued). "Since miR-21-5p directly targets DSCR9 and the BTG2 3′UTR, the dynamic effects of DSCR9 and miR-21-5p on BTG2 expression and pancreatic cancer cell phenotype were examined to determine whether DSCR9 and miR-21-5p exert their functions via BTG2." (PMID 36789695, 2022). "Among them, lncRNA DSCR9 showed the lowest Hazard Ratio (HR, 0.29,P<0.01), suggesting that DSCR9 might be a protective factor in pancreatic cancer patients." (PMID 36789695, 2022). "Moreover, FISH and IF staining results showed that both BTG2 (green fluorescence) and DSCR9 (red fluorescence) levels were upregulated in adjacent tissues compared to those in pancreatic cancer tissues." (PMID 36789695, 2022). "The lncRNA DSCR9 showed a significant reduction in pancreatic cancer tissue samples and cells." (PMID 36789695, 2022). "Thus,BTG2 functions as an antiproliferative gene in tumorigenesis and the effect of DSCR9 in pancreatic cancer cells might be related to BTG2." (PMID 36789695, 2022). "After confirming the binding of miR-21-5p to DSCR9 and the BTG2 3′UTR, the specific roles of miR-21-5p in the pancreatic carcinoma phenotype were validated." (PMID 36789695, 2022). "Overexpression of miR-21-5p attenuates the effect of DSCR9 overexpression on BTG2 expression and invasiveness of pancreatic cancer cells." (PMID 36789695, 2022). "The CoxPH model showed that higher DSCR9 expression was correlated with better overall survival and better recurrence-free survival (RFS) in subjects with pancreatic cancer." (PMID 36789695, 2022). "Immunofluorescence (IF) staining combined with fluorescencein situ hybridization (FISH) of pancreatic cancer tissues shows that DSCR9 and BTG2 are both increased in pancreatic cancer tissues." (PMID 36789695, 2022). "Next, we examined DSCR9 expression in 15 paired collected pancreatic carcinoma and noncancerous tissue samples." (PMID 36789695, 2022). "To validate the role of DSCR9 in pancreatic carcinoma cell resistance to gemcitabine, we treated noninfected, lv-NC-infected, or lv-DSCR9-infected PANC-1 and MIAPaCa-2 cell lines with gemcitabine (10 μM) for 48 h and examined cell apoptosis." (PMID 36789695, 2022). "DSCR9 expression was significantly downregulated in 40 pancreatic carcinoma tissue samples compared with that in 40 paired noncancerous tissue samples." (PMID 36789695, 2022). "In addition, based on the microarray expression profile GSE16515, DSCR9 expression was also significantly downregulated in 36 pancreatic carcinoma tissue samples compared with that in 16 noncancerous tissue samples." (PMID 36789695, 2022).
prostate carcinoma (1 paper, 2011). A carcinoma that arises from epithelial cells of the prostate gland. "A few of these (regions associated with ADAMTS1, SCARF2, and DSCR9) were tested further, and in combination, showed ~100% sensitivity and ~85% specificity for prostate cancer compared to matched adjacent benign tissues." (PMID 21669002, 2011).
cancer (3 papers, 2018 to 2022). A tumor composed of atypical neoplastic, often pleomorphic cells that invade other tissues. "No direct evidence had been reported so far to illustrate that DSCR9 was responsible for cancer progressing." (PMID 29351810, 2018). "There are less studies for C9orf163 and DSCR9 in the context of cancer." (PMID 33061845, 2020). "In addition, our experimental data supported the predicted DSCR9 regulation of its target genes in two different cancer cell lines, i.e., A549 and U251." (PMID 29351810, 2018). "In summary, the COIN analysis results indicated that DSCR9 was highly correlated with several oncogenes and therefore it was very likely that its regulatory function could be employed to explain the reduced cancer incidence in patients with DS." (PMID 29351810, 2018).
neurological diseases (2 papers, 2018 to 2020). "The results provided a valuable guidance for further investigations on the regulatory mechanism of DSCR9 as well as its relevance to DS and other neurological diseases." (PMID 29351810, 2018). "DSCR9 was highly correlated with genes that were known as important factors in the development and functions of the nervous system, suggesting that DSCR9 can regulate proteins related to DS and other neurological diseases." (PMID 31918411, 2020).
tumor (2 papers, 2020 to 2022). "The expression of DSCR9 was dramatically decreased in tumor tissue samples." (PMID 36789695, 2022). "These suggested LINC00476, c9orf163 and DSCR9 might act as tumor suppressors in PC." (PMID 33061845, 2020).
DSCR9 also shares sentences with these, for which no sentence is quoted: colon carcinoma (1 paper); prostate adenocarcinoma (1); rheumatoid arthritis (1).